INS (insulin)
Diseases named in the same sentence as INS in open-access papers (continued):
Sharing a sentence is not in itself a finding about the gene and the disease.
diabetes (continued). "In summary, dietary carbohydrate restriction in conjunction with metformin and liraglutide treatment is an effective treatment option for patients with advanced diabetes who are scheduled to switch to insulin or who are in need of intensified insulin treatment to regain metabolic control." (PMID 22196251, 2011). "Furthermore, TRIB3 has a role in insulin sensitivity and diabetes and has also been described to interact as a scaffold protein in multiple signaling cascades, including v-akt murine thymoma viral oncogene homolog 1 (PKB/Akt) but also MAPK pathways." (PMID 21864376, 2011). "Human insulin is a major backbone for the treatment of diabetes." (PMID 22187651, 2011). "Post-transplant diabetes mellitus was diagnosed and insulin therapy was initiated." (PMID 22032472, 2011). "Indeed, successful restoration of insulin independence following allotransplantation of islets from a single donor per recipient has been reported in eight diabetes patients." (PMID 22235361, 2011). "Insulin's effect on inflammation could explain in part why local insulin was able to reduce the Müller cell activation observed in diabetes." (PMID 22046295, 2011). "Therefore, preventing and treating efforts for the non-insulin taking patients in the stage of pre-diabetes and diabetes are urgently needed to lift the burden from both the nation and patients." (PMID 21310088, 2011). "Diabetic patient who had uncontrolled diabetes was managed by insulin." (PMID 21854557, 2011). "This may result in two beneficial effects in diabetes: Firstly, induction of anti-apoptotic genes will probably stimulate beta-cell survival and insulin production." (PMID 21935477, 2011). "Lack of local trophic insulin action causing acinar atrophy does not explain the fact that most patients with type 1 diabetes mellitus have no signs of exocrine changes." (PMID 21822421, 2011). "The median duration of diabetes was 7.0 years, with 18% reporting treatment with insulin." (PMID 22164161, 2011). "Based on our accumulated evidence, we hypothesized a model that PIHO, an essential post-translational regulation mechanism in insulin biosynthesis, may critically link to diabetes." (PMID 21559376, 2011). "Normalization of blood glucose and increased local retinal insulin levels both reversed the diabetes-induced retinal cell death in correlation with the reversal of retinal insulin signaling as demonstrated by complete or partial restoration of IR and Akt1 kinase activity." (PMID 22046295, 2011). "Therefore the present study was performed to evaluate the effectiveness of OPE in modulating hyperglycemia and insulin-insensitivity by using a high fat diet (HFD)/streptozotocin (STZ)-induced diabetic rat model." (PMID 21439094, 2011). "After exclusion of all participants with diabetes, the association remained significant for glucose (P=0.001), but became non-significant for insulin (P=0.209)." (PMID 21191145, 2011). "Insulin therapy has revolutionized the treatment of diabetes mellitus (DM) and has contributed to increased longevity and improved quality of life for people with diabetes." (PMID 21754922, 2011). "It is exactly what happened with diabetes mellitus after the discovery of insulin in 1921." (PMID 21556173, 2011). "Therefore, body mass index and insulin use of the study subjects should be considered when the prevalence of HUA is discussed in patients with type 2 diabetes mellitus." (PMID 22125626, 2011). "Therapeutic strategies that limit nutrient levels and/or augment ocular insulin action may enhance the prognosis for vision in persons with diabetes." (PMID 22046295, 2011). "It has been postulated that IGF-I might enhance insulin secretion and sensitivity, stimulate β cell regeneration as well as prevent β cell from apoptosis in patients with diabetes." (PMID 21486461, 2011).
diabetes (continued). "On the one hand, IDE's established role in insulin catabolism predicts that IDE inhibition should increase the half-life of circulating insulin, an effect that could be beneficial for the treatment of diabetes." (PMID 21695259, 2011). "We've gradually lost territory to the specialists, e.g. patients on insulin therapy could suddenly get all their material for free in diabetes centres." (PMID 21902832, 2011). "Since Insulin suppresses hepatic glucose output by stimulating glycogen synthesis and inhibiting glycogenolysis and gluconeogenesis, a drug that would stimulate the insulin production or sensitize the peripheral tissues to insulin would be of beneficial effect to treat Diabetes Mellitus." (PMID 20924498, 2011). "In addition, decreased insulin secretory capacity, decreased ATP production and abnormalities in mitochondrial morphology have been found in isolated islets from mouse models of diabetes and patients with type 2 diabetes." (PMID 21886784, 2011). "Diabetes mellitus (DM) is a group of metabolic disorders characterized by hyperglycemia, with disturbances of carbohydrate, fat, and protein metabolism resulting from defects in insulin secretion, insulin action, or both." (PMID 20981320, 2011). "Among survivors, 38% were left with permanent diabetes requiring insulin." (PMID 21798000, 2011). "In this study we tested the hypothesis that increased retinal insulin signaling and glycemic normalization would exert differential effects on retinal cell survival and retinal physiology during diabetes." (PMID 22046295, 2011). "The majority of GWAS findings to date highlight variants associated with fasting glucose and diabetes status rather than fasting insulin and HOMA-IR levels." (PMID 21901158, 2011). "Knowing the answers to these questions might ultimately lead to novel means to preserve or restore insulin production capacity in prevention and treatment of diabetes." (PMID 22102916, 2011). "The First Basal Insulin Evaluation (FINE) Asia study is a multinational, prospective, observational study of insulin-naïve Type 2 diabetes mellitus (T2DM) patients in Asia, uncontrolled (A1c ≥ 8%) on oral hypoglycemic agents, designed to evaluate the impact of basal insulin initiation." (PMID 21631903, 2011). "For example, in insulin-resistant states, such as obesity and type II diabetes, insulin-stimulated glucose uptake is markedly impaired, while increasing the number of type I fibres enhances insulin-mediated glucose uptake and protects against diabetes and other metabolic diseases." (PMID 21193034, 2011). "Finally, older rural adults with diabetes receiving less than adequate care were less likely to use insulin (OR = .494 95% CI .487-.502) or have an elevated BMI." (PMID 22177279, 2011). "The significantly higher use of insulin by public compared to private patients may reflect the fact that public patients have been diagnosed with diabetes longer." (PMID 21676257, 2011). "So ozone therapy may be considered as an adjuvant to insulin in the treatment of diabetes to prevent or alleviate diabetes induced nephropathy." (PMID 20465785, 2010). "The Italian study group on early onset diabetes has detected two INS mutations (A23S and G23S) in children negative for 5 type 1 diabetes (T1D) autoantibodies." (PMID 20226046, 2010). "Many endocrinologists were also confronted with this problem when investigating diabetes mechanism after administration of exogenous insulin antiserum or when investigating the physiological role of oPL following active immunization of ewe-lambs against recombinant oPL." (PMID 20128904, 2010). "As insulin has been described to be involved in the metabolism of both Aβ and tau, the researcher studied the possible effect of artificially induced Diabetes mellitus (DM) on the brain cells of pR5 transgenic mice which expressed the P301L human mutant tau and produced neurofibrillary tangles." (PMID 20721342, 2010).
diabetes (continued). "Oral insulin may improve β-cell function by providing β-cell rest, and may help in preventing diabetes via induction of 'oral tolerance' or immuno modulation." (PMID 21059246, 2010). "LV changes were paralleled by RV alterations in insulin-stimulated glucose utilisation and RV systolic function in a rat model of diabetes, which may be attributed to ventricular interdependence as well as to the uniform effect of diabetes." (PMID 20550678, 2010). "Besides the necessary equipment for the diabetes treatment at home e.g. blood glucose meter and dextrose, during the first home leave and also subsequently insulin, the family was given the phone number to the PDSN." (PMID 20507611, 2010). "Further, the present data suggest that if these animals were studied when aged (e.g., 12 months or beyond), early deficits in renal, glucose/insulin and autonomic dysregulation may lead to insulin resistance, diabetes, and hypertension." (PMID 20804607, 2010). "As the aortic elasticity changes in the prediabetic state are limited to subjects with insulin resistance, the use of insulin-sensitizing agents to prevent diabetes could have a beneficial effect on CVD." (PMID 21811521, 2010). "Sometimes, therapeutic interventions may have unintended consequences on other diseases, such as the increased mortality rates observed in diabetes with intensive insulin regimens." (PMID 20500815, 2010). "It has been demonstrated that resistin impairs glucose tolerance and antagonizes insulin action, indicating that resistin may be an important cytokine linking obesity to diabetes." (PMID 21113299, 2010). "At 12 months, insulin therapy was an effective strategy in reducing HbA1c in a population with a very diverse duration of diabetes (SD 5–6 years), but the reduction of a little over 1.0% is somewhat disappointing compared with treat-to-target studies, despite similar insulin doses at 1 year." (PMID 20946269, 2010). "In animal models of diabetes, resveratrol reduced blood insulin levels and hyperglycemia." (PMID 22254051, 2010). "However, commensurate with the projected escalation in the prevalence of diabetes in the coming decades, there will be an increasing demand for insulin." (PMID 20462406, 2010). "Glucose Tolerance Testing, insulin, HbA1c, blood pressure measurements and plasma lipids further characterized the diabetes in relation to criteria of the Metabolic Syndrome, while diet modification with high-fat, low-fiber or food restriction attempted to modulate the disease." (PMID 20398338, 2010). "Previous studies have suggested that minority groups (eg, African Americans, Hispanics, American Indians, Pacific Islanders) and adults who have had diabetes for a long time, who have comorbidities, or who use insulin or multiple oral agents have high HbA1c levels." (PMID 20040223, 2010). "Genetic deletion of one, two, or even three alleles encoding insulin in mice does not necessarily lead to diabetes." (PMID 20948967, 2010). "Of particular importance for IIS, insulin resistance and failure in insulin production can result in diabetes in mammals, with its consequent vascular damage, while the invertebrates, with their open circulatory systems, can probably better tolerate elevated blood sugar." (PMID 20008392, 2010). "Four single nucleotide polymorphisms (SNPs) (rs2237892, rs2237895, rs2237897, and rs2283228) in KCNQ1 are reported to be associated with type 2 diabetes mellitus (T2DM), possibly caused by a reduction in insulin secretion and higher fasting glucose, but the results are inconsistent." (PMID 20701788, 2010). "Furthermore, we excluded patients treated with 3 or more insulin injections a day (8.6% of the diabetes patients on medication in 2003), in order to limit the presence of type 1 diabetes patients in the study cohorts." (PMID 20630062, 2010).
diabetes (continued). "As the silent ischemic changes in the prediabetic state are limited to subjects with insulin resistance, the use of insulin-sensitizing agents to prevent diabetes could have a beneficial effect on CVD." (PMID 21187864, 2010). "An important observation from the San Antonio Heart Study was that several independent predictors of diabetes that were present before the onset of hyperglycaemia were correlated with each other, including elevated BMI and insulin levels, hypertriglyceridaemia, hypertension and lower HDL-C." (PMID 20233452, 2010). "The FLI may be viewed as an indirect marker of impaired insulin secretion, one of the major determinants of incident diabetes." (PMID 20529259, 2010). "A 35 year-old Iraqi male was referred to our diabetes clinic for insulin-treated DM, impaired renal function with a serum creatinine level of 188 mmol/L (normal reference range is 45-105 mmol/L), gross proteinuria of 2.7 g/day, and a fasting blood sugar level of 13.7 mmol/L (RR is 3.9-6.1 mmol/L)." (PMID 20103962, 2010). "Alterations in blood glucose and insulin levels in people with diabetes may impair the function of the vestibular system making it difficult for them to detect minor postural disturbances." (PMID 20836855, 2010). "Further we extended the studies to phospholipase C regulation with curcumin supplementation and insulin treatment a potential therapeutic drug which can modulate signal transduction pathway there by contributing in the prevention of CNS dysfunction in diabetes." (PMID 20513244, 2010). "This is believed to be the first abnormality in diabetes, preceding insulin secretion failure." (PMID 20718958, 2010). "High basal plasma glucose levels and simultaneously low insulin sensitivities also occur in humans suffering from non-insulin-dependent diabetes mellitus (NIDDM), so the insulin sensitivity of camels may be similar to that of NIDDM patients." (PMID 20502665, 2010). "Even if obesity and diabetes-related proteins are not directly linked to heart-disease proteins, rich indirect linkages can be realized through, for example, the insulin signaling pathway or the P12931 proto-oncogene tyrosine-protein kinase Src." (PMID 20670417, 2010). "The groups differ in age (∼10 years), diabetes duration (∼20 years), and medication (e.g. insulin)." (PMID 20975990, 2010). "The present results in insulin and glucose metabolism clearly indicate that the surveillance of such individuals must not be neglected since they have increased risk of diabetes in the future." (PMID 21318152, 2010). "Moreover, possible risks for malignancies in patients with diabetes treated with human insulin or insulin analogues have recently been reported." (PMID 21048849, 2010). "However, many experimental studies have been performed to evaluate the effects of mild diabetes, with divergent results regarding glycemia and insulin measurement, presence of fetal macrosomia and placental weights." (PMID 20529353, 2010). "Diabetes pathogenesis involves many pathways operating in different tissues and distinct physiological processes (blunted insulin signaling and failure of beta cells to compensate by producing more insulin)." (PMID 20463879, 2010). "In the recent SAPS III study, diabetes, with or without insulin treatment, was associated with a worse hospital mortality in multivariate analysis." (PMID 20132545, 2010). "Providing people access to insulin and oral medication as well as diabetes services is important in order for them to engage continuously in treatment and a female informant addressed the problem of gaining access to medication and treatment in a focus group discussion in this manner." (PMID 20441575, 2010). "How does diabetes treatment satisfaction differ among those individuals whose expectations about insulin therapy are exceeded by experiences with insulin therapy, those whose expectations are met by their experiences, and those whose expectations are not met by their experiences?" (PMID 20370840, 2010).
diabetes (continued). "Yet MIDY patients are INS-gene heterozygotes; inheritance of even one MIDY allele, causes diabetes." (PMID 20948967, 2010). "The increased postprandial insulin secretion and the apparently improved hepatic insulin sensitivity may both contribute to the better glycemic control and prevention of full-fledged diabetes in leucine-treated RCS10 mice." (PMID 20624298, 2010). "In addition, self-monitoring should be supported by the diabetes team through discussion of results with patients during each clinic visit to help improve the efficacy and safety of insulin therapy." (PMID 20456170, 2010). "The limited availability of cadaveric human donor pancreata as well as the incomplete success of the Edmonton protocol for human islet allografts fasten search for new sources of insulin the producing cells for substitution cell therapy of insulin-dependent diabetes mellitus (T1DM)." (PMID 21048849, 2010). "In diabetes, fear of hypoglycaemia is specifically important as it is not only a subjective nuisance, but it may also affect patients' insulin regimen and eating habits." (PMID 21110902, 2010). "It is well known that the number of INS-positive cells is decreased in diabetes." (PMID 20062799, 2010). "While the risk of hypoglycemia is particularly elevated in patients receiving insulin therapy, patients with type 2 diabetes mellitus (T2DM) treated with insulin secretagogues (e.g., sulfonylureas, meglitinides) are also at increased risk of experiencing hypoglycemic symptoms." (PMID 20723229, 2010). "Quantification of glycogen in the liver and skeletal muscle further confirms the efficacy of ‘Diashis’ for the recovery of diabetes, which, in turn, supports the insulinotropic effect of ‘Diashis’, as insulin is the main regulator of glycogen content in liver and skeletal muscle." (PMID 20532093, 2010). "Thus the IITQ incorporates elements that allow for comparisons among all diabetes therapies, among all insulin therapies, and among all inhaled insulin therapies." (PMID 20334647, 2010). "In human diabetes, the decrease of availability of both insulin and C-peptide could change the regulatory equilibrium of NKA activity in favor of a decrease." (PMID 22457695, 2010). "Diabetes mellitus is a metabolic disorder of multiple etiologies characterized by chronic hyperglycemia with impairment of carbohydrate, fat and protein metabolism resulting from defects in insulin secretion, insulin action, or both." (PMID 20180965, 2010). "• Reduce insulin immediately after the birth in women with insulin treated pre-existing diabetes." (PMID 20416099, 2010). "Three of the eight tests of change in means were significant (Perceptions of Insulin Therapy and Treatment Preference for type 1 and Diabetes Worries for type 2), but the size of the change was small (less than 0.1 standard deviation units, a measure of effect size)." (PMID 20334647, 2010). "Insulin resistance in metabolically relevant insulin target tissues, such as skeletal muscle, liver, adipose tissue and more recently the brain, represents a well-studied key characteristic during the development of type 2 diabetes mellitus." (PMID 20463885, 2010). "Metformin is recommended as a core therapy in diabetes management worldwide at diagnosis and is seen as being complementary to lifestyle change either alone or in combination with other oral antidiabetic therapies or insulin." (PMID 20298568, 2010). "To summarize, in a large general population sample of adults without diabetes or coronary heart disease, we found lower levels of 25(OH)D to be associated with higher levels of fasting glucose, insulin and SBP and lower levels of HDL-c." (PMID 21085485, 2010). "Is your diabetes treated with insulin and other medications?" (PMID 21092171, 2010). "In both insulin dependent and insulin independent diabetes, there is increased oxidative stress." (PMID 21218075, 2010).